SLC38A2 (solute carrier family 38 member 2)
Diseases named in the same sentence as SLC38A2 in open-access papers (continued):
Sharing a sentence is not in itself a finding about the gene and the disease.
cancer (continued). "Furthermore, hSPAR/hSPAR-C also serves as an inhibitor of glutamine transporter SLC38A2 expression and thereby decreases the cellular glutamine levels specifically in cancer cells." (PMID 39875724, 2025). "Time-dependent AUC results indicate that SLC38A2 has a higher predictive value in three types of cancer that include DLBC (1-year AUC = 0.792, 5-year AUC = 0.757), KICH (1-year AUC = 0.898, 3-year AUC = 0.766, 5-year AUC = 0.790), and PAAD (5-year AUC = 0.739)." (PMID 41040664, 2025). "After determining that SLC38A2 exhibits altered expression in cancer, we analyzed whether this gene affects cancer prognosis." (PMID 41040664, 2025). "Our research hypothesizes that SLC38A2 functions as a broadly significant immune and prognostic biomarker in cancer, potentially serving as a target for therapeutic intervention." (PMID 41040664, 2025). "Moreover, glutamine is the main nutrient used by cancer cells in energy metabolism, which indicates the importance of SLC38A2 in cancer metabolism." (PMID 36918802, 2023). "While additional cell context-specific alterations induced by SMARCA4/2-loss may also contribute to the metabolic reprograming, our results support the pivotal role of GLUT1/SLC38A2 underlying the glutamine and OXPHOS dependency of these cancer cells." (PMID 37210563, 2023). "Furthermore, supplementation of alanine, also imported by SLC38A2, restricts glutamine uptake through competition and selectively induces death in SMARCA4/2-deficient cancer cells." (PMID 37210563, 2023). "The import of 90% of the net amino acid demand is mediated directly or indirectly by SNAT1 (SLC38A1) and SNAT2 (SLC38A2), because they are the main neutral amino acid loaders in cancer cells and provide exchange substrates for antiporters to capture amino acids not transported by SNAT1 and SNAT2." (PMID 32859034, 2020). "Among the top anticorrelated genes were SLC38A2 and CDC42, the latter of which has previously been shown to be downregulated by MIR137 in cancer cells." (PMID 40964041, 2025). "Amino acid transporters like the sodium-coupled neutral amino acid transporter 2 (SNAT2, SLC38A2) have gained interest for their roles in, e.g., the central nervous system and in cancer." (PMID 40775108, 2025). "In cancer, NFYC has been shown to modulate SREBF-driven pathways, linking it to the transcriptional control of metabolic genes such as DHCR7 and SLC38A2, both of which were also observed in our model." (PMID 40941703, 2025). "Several SLC38 isoforms have previously been linked to cell proliferation, invasion, migration and/or angiogenesis, including SLC38A2, SLC38A3, SLC38A6 and SLC38A7, supporting their involvement in cancer progression." (PMID 38254895, 2024). "Mechanistically, LINC01614 directly interacts with ANXA2 and p65 to facilitate the activation of NF-κB, which leads to the upregulation of the glutamine transporters SLC38A2 and SLC7A5 and eventually enhances the glutamine influx of cancer cells." (PMID 36209111, 2022). "It has been described that hypoxia enhances glutamine synthesis and uptake in cancer cells by increasing glutamine synthetase (GS, also known as GLUL) and the number of glutamine transporters such as SLC38A2." (PMID 35408935, 2022). "Here are just a few examples: SNAT1 (SLC38A1), SNAT2 (SLC38A2), and ASCT2 (SLC1A5) are the major Gln transporters in cancer cells." (PMID 33477430, 2021). "The transporters that stand out as potential targets to reduce cancer cell growth are ASCT2 (SLC1A5), LAT1 (SLC7A5), CAT1 (SLC7A1), GC1 (SLC25A22), and SNAT2 (SLC38A2)." (PMID 32859034, 2020). "Data from the DepMap database show high expression levels of SLC1A5, SLC7A11, SLC38A2, and SLC7A5 in the selected cancer cell lines." (PMID 33400734, 2020). "Data from the human Cancer Cell Line Encyclopedia (CCLE) demonstrated differential expression of these genes across cell lines, with high expression of PHGDH, PSAT1, SLC1A5 and SLC38A2, and low expression of SLC38A4 and SLC7A10." (PMID 40660426, 2025).
cancer (continued). "The results of the unpaired sample differential analysis indicate that SLC38A2 exhibits differential expressions in 14 types of cancer tissues compared to adjacent non-cancerous tissues." (PMID 41040664, 2025). "The analysis of non-paired samples revealed that the expression of SLC38A2 differs in 15 cancer types compared to their corresponding normal tissues, indicating altered expression in cancerous tissues." (PMID 41040664, 2025). "Moreover, we demonstrate that alanine, a natural and non-toxic amino acid, can be used to compete with glutamine for SLC38A2-mediated uptake leading to suppression of glutamine metabolism and OXPHOS in these cancer cells." (PMID 37210563, 2023). "While SLC38A2 also mediates alanine uptake, alanine deprivation did not impact the growth of SMARCA4/2-deficient cancer cells, supporting the dominant contribution of glutamine in this context." (PMID 37210563, 2023). "SLC6A14 (ATB0,+) that broadly accepts large neutral amino acids, as well as SLC38A2 (SNAT2), SLC38A3 (SNAT3) and SLC38A7 (SNAT7) that accept some large neutral amino acids such as His, Met and Leu are known to be upregulated in certain types of cancers." (PMID 36071551, 2022). "Furthermore, it has been demonstrated that SLC38A1/SNAT1 and SLC38A2/SNAT2 activity is essential to mediate net glutamine uptake and glutaminolysis in cancer cells, whereas SLC1A5/ASCT2 and SLC7A5/LAT1 coordinate intracellular amino acid pools." (PMID 34003553, 2021). "Because the anti-oxidant N-acetylcysteine (NAC) was shown to mitigate ROS production in cancer cell lines, we postulated that exogenous supplementation of NAC might reduce the anti-growth effects of SLC38A2 blockade." (PMID 33028955, 2021). "miR-199b-5p targets solute carrier transporters (SLC1A2/EAAT2 in astrocytes and SLC38A2/SNAT2 and SLC16A7/MCT2 in neurons) to hijack the neuron–astrocyte metabolic coupling, leading to extracellular retention of these metabolites and promoting cancer cell growth." (PMID 38811525, 2024). "Thus, our data unveil the upregulation of the selected AATs (SLC1A5/ASCT2, SLC7A5/LAT1, and SLC38A2/SNAT2) as a prognostic marker of poor survival of patients with CRC, useful for cancer patient stratification, in particular with regard to the KRAS mutant subtype of patients." (PMID 34003553, 2021). "However, restoration of SMARCA4 or SMARCA2 in SMARCA4/2-deficient cells did not consistently suppress SLC38A2 expression, suggesting that the elevated SLC38A2 levels in SMARCA4/2-deficient cancer cells may be an adaptation to suppressed glycolysis rather than a direct transcriptional regulation." (PMID 37210563, 2023).
infection (7 papers, 2017 to 2025). The state of being infected such as from the introduction of a foreign agent such as serum, vaccine, antigenic substance or organism. "In support of this, Ad-SLC38A2 infection conferred cytoprotection against hyperosmolarity-induced cell death in both WT and Slc38a2 gene-deficient primary IMCD cells." (PMID 36722887, 2023). "In contrast to SLC38A2, 22 proteins were identified at reduced levels on the host cell surface during infection." (PMID 30190327, 2018). "While other solute carrier family genes were upregulated following infection, solute carrier family 38 member 2 (SLC38A2) was downregulated following infection in both strains." (PMID 29085037, 2017). "In addition to proteins with increased cell-surface levels, like SLC38A2, we also identified 22 cell-surface proteins that were found at reduced levels during infection." (PMID 30190327, 2018).
adenocarcinoma (2 papers, 2016 to 2026). A common cancer characterized by the presence of malignant glandular cells. "PCK2 and SLC38A2 were highly expressed in human adenocarcinomas tissues." (PMID 41769368, 2026). "We assessed the expression of Na+-solute co-transporters, members of the SLC5 family and the Na+-driven glutamine transporters SLC38A1 and SLC38A2, in human NSCLC (adenocarcinoma) samples compared to normal lung tissue using a large, public dataset published at GEO (GDS3257)." (PMID 27294516, 2016).
SLC38A2 also shares sentences with these, for which no sentence is quoted: osteosarcoma (4 papers); gastric cancer (3); ovarian carcinoma (3); sarcopenia (3); type 2 diabetes (3); multiple myeloma (2); Ataxia (1); ataxia telangiectasia (1); bacterial infection (1); bladder cancer (1); breast adenocarcinoma (1); cervical cancer (1); cholestasis (1); colon adenocarcinoma (1); depression (1); endometrial carcinoma (1); endometrioid adenocarcinoma (1); esophageal cancer (1); folate deficiency (1); glioma (1); hepatoma (1); Hyperglycemia (1); hyperhomocysteinemia (1); hypertensive disorder (1); hypertriglyceridemia (1); Hyponatremia (1); lactic acidosis (1); lung adenocarcinoma (1); metabolic syndrome (1); metastatic tumours (1).
A further 6 diseases each share a sentence with SLC38A2 in 1 paper.